MKRN2 (makorin ring finger protein 2)
Diseases named in the same sentence as MKRN2 in open-access papers:
MKRN2 is named in the same sentence as 39 diseases in open-access papers, as found by Europe PMC text mining. Sharing a sentence is not in itself a finding about the gene and the disease. The quoted sentences say what the papers report.
infertile (3 papers, 2016 to 2023). "These two independent cohorts provide direct evidence indicating that MKRN2 is significantly correlated with infertility in men." (PMID 28008940, 2016). "Furthermore, the Mkrn2 expression levels were significantly downregulated in the infertile male subjects in our study." (PMID 28008940, 2016). "The results showed that the expression levels of MKRN2 and STAT1 were both significantly downregulated in the infertile patients." (PMID 36967804, 2023). "To verify the role of MKRN2 in the male teratozoospermia, we analyzed the expression levels of MKRN2 and STAT1 in 13 normally fertile male patients and eight infertile individuals with a severe and consistent heterogeneous teratozoospermia based on the GEO dataset GSE6872." (PMID 36967804, 2023).
leukemia (3 papers, 2014 to 2022). A malignant (clonal) hematologic disorder, involving hematopoietic stem cells and characterized by the presence of primitive or atypical myeloid or lymphoid cells in the bone marrow and the blood. "In primary leukemia cells and in different leukemia cell lines, enhanced MKRN2 expression results in reduced apoptotic rates and enhanced cell proliferation." (PMID 34257800, 2021). "The expression levels of MKRN2 were generally higher in leukemia samples (P<0.05 in Ph–B-ALL, Ph+B-ALL, T-ALL and AML samples) compared with those in age-matched normal BM cells (n = 9), whilst RAF1 was higher in Ph–B-ALL and AML samples (P<0.05)." (PMID 24675897, 2014). "In primary leukemia samples obtained from BM of patients, we showed positive expressions of MKRN2 and RAF1 in B-ALL Philadelphia chromosome (BCR/ABL or Ph) positive and negative, T-ALL, AML and CML samples (n = 5–22)." (PMID 24675897, 2014). "Our results provided the first evidence on the ubiquitous expression of MKRN2 in normal hematopoietic cells, embryonic stem cell lines, primary leukemia and leukemic cell lines of myeloid, lymphoid, erythroid and megakaryocytic lineages." (PMID 24675897, 2014). "It is anticipated that a larger sample size of each leukemia subtype would be required to accurately address the relationship between MKRN2 and RAF1, as well as between specific translocations such as BCR-ABL." (PMID 24675897, 2014). "Upregulated expressions of MKRN2 in primary leukemia cells prompted us to further investigate the effects of forced expression and silencing of MKRN2 in the leukemic cell line K562." (PMID 24675897, 2014). "The expression levels of MKRN2 were generally higher in primary leukemia samples compared with those in age-matched normal BM cells." (PMID 24675897, 2014). "MKRN2 expression was greater in primary leukemia samples than in age-matched normal BM cells." (PMID 35463379, 2022). "We also demonstrated expressions of MKRN2 and RAF1 in leukemia cell lines of B-ALL, T-ALL, AML, CML, NK and MK lineages (n = 2–3)." (PMID 24675897, 2014). "We investigated the expression levels of MKRN2 and RAF1 in normal and malignant hematopoietic cells, and leukemia cell lines." (PMID 24675897, 2014). "Our results demonstrated ubiquitous mRNA expression of MKRN2 and RAF1 in normal hematopoietic cells, embryonic stem cell lines, primary leukemia and leukemic cell lines." (PMID 24675897, 2014).
lung carcinoma (3 papers, 2018 to 2025). "MKRN2 also exhibits anti-tumor action, inhibiting lung cancer development via blocking the PI3k/Akt pathway." (PMID 40959281, 2025). "Because MKRN2 levels correlated with NSCLC progression, we explored the biological function of MKRN2 in lung cancer cells by genetically manipulating MKRN2 expression." (PMID 30103781, 2018). "As known, MKRN2 was involved in ubiquitin-dependent degradation of the p85α subunit of PI3K (PI3Kp85α) in lung cancer; additionally, several studies reporting that MKRN2 is a novel ubiquitin E3 ligase targeting the p65 subunit of NF-κB to inhibit the inflammatory response." (PMID 35196650, 2022).
male infertility (3 papers, 2016 to 2023). The inability of the male to effect fertilization of an ovum after a specified period of unprotected intercourse. "The results of our study provided insights into a new mechanism of male infertility caused by the MKRN2 downregulation." (PMID 28008940, 2016). "Next, we investigated the molecular mechanism of Mkrn2 deficiency leading to male infertility." (PMID 28008940, 2016). "All of these results indicated that MKRN2-regulated STAT1 is involved in the process of male infertility." (PMID 36967804, 2023). "We developed a Mrkn2 knockout mice model to study this gene and found that deletion of Mkrn2 in mice led to male infertility." (PMID 36967804, 2023). "The results of our study will provide insights into a new mechanism of MKRN2 in regulating male infertility." (PMID 36967804, 2023). "These two independent cohorts demonstrated that low MKRN2 expression levels in sperm are strongly correlated with human male infertility." (PMID 28008940, 2016). "We developed an Mrkn2 knockout mouse model to study the role of this gene, and found that deletion of Mkrn2 in mice led to male infertility." (PMID 28008940, 2016). "Few reports have focused on the regulation of MKRN2 in male infertility." (PMID 36967804, 2023). "We then determined why Mkrn2 deletion leads to male infertility." (PMID 28008940, 2016). "In this study, we found a new regulatory mechanism between MKRN2 and STAT1/SIX4/TNC, which is a novel mechanism of MKRN2 in regulating male infertility." (PMID 36967804, 2023). "Thus, we wonder how to evaluate the regulatory mechanism between MKRN2 and STAT1/SIX4/TNC to figure out the novel mechanism of MKRN2 in male infertility." (PMID 36967804, 2023). "In this study, we plan to address: (a) the role of MKRN2 in male infertility; (b) whether MKRN2 regulates the expression level of STAT1; and (c) how MKRN2 induces the expression levels of SIX4 and TNC by the transcription factor EBF transcription factor 2 (EBF2)." (PMID 36967804, 2023).
neuroblastoma (3 papers, 2022 to 2024). Neuroblastoma (NB) is the most common solid, extracranial childhood tumor. "In neuroblastoma, MKRN2 down‐regulated the expression of IGF2BP3‐targeted downstream pathways, indicating a negative regulatory effect of ubiquitination on IGF2BP3 function." (PMID 37877353, 2023). "Makorin ring finger protein (MKRN2) regulates its downstream molecules in an IGF2BP3‐dependent manner in neuroblastoma, indicating the ubiquitination modification of IGF2BP3." (PMID 37877353, 2023). "As a result, MKRN2 may be a promising therapeutic target for neuroblastoma." (PMID 35463379, 2022). "MKRN2, an E3 ligase, was found to be involved in the ubiquitination of IGF2BP3 in neuroblastoma." (PMID 38565547, 2024).
lymph node metastasis (2 papers, 2018 to 2023). "We demonstrated that MKRN2 expression was associated with lymph node metastasis, p-TNM stage, cancer-cell differentiation, and poor prognosis." (PMID 30103781, 2018). "Previous studies have reported that MKRN2 inhibits the cell migration and invasion of non-small cell lung cancer by downregulating the PI3K/Akt pathway and is associated with lymph node metastasis, TNM stage, and cell differentiation." (PMID 36967804, 2023). "Based on the relationships between lymph node metastasis and MKRN2 expression in clinical cases and the functions of MKRN2 in NSCLC cell migration and invasion, we investigated the specific biological mechanisms associated with these effects." (PMID 30103781, 2018).
melanoma (2 papers, 2021 to 2022). A malignant, usually aggressive tumor composed of atypical, neoplastic melanocytes.
non-small cell lung carcinoma (2 papers, 2018 to 2023). A group of at least three distinct histological types of lung cancer, including non-small cell squamous cell carcinoma, adenocarcinoma, and large cell carcinoma. "In this study, we clarified the role of MKRN2 in non-small cell lung cancer (NSCLC)." (PMID 30103781, 2018).
Anosmia (1 paper, 2023). An inability to perceive odors. "MKRN2, together with G3BP1/2, has been suggested to regulate olfactory signaling mRNAs25, pointing to potential mechanistic links underlying anosmia in COVID-19." (PMID 36217029, 2023).
autism spectrum disorder (1 paper, 2026). A spectrum of developmental disorders that includes autism, and Asperger syndrome. "Mkrn2-knockout mice exhibited sex-specific social abnormalities-increased sociability in males and social withdrawal in females-recapitulating autism-spectrum disorder (ASD) heterogeneity." (PMID 41757349, 2026).
Azoospermia (1 paper, 2023). Absence of any measurable level of sperm,whereby spermatozoa cannot be observed even after centrifugation of the semen pellet. "We then analyzed the MKRN2 expression level of four normal spermatogenesis individuals (normal) and 27 nonobstructive azoospermia samples (patients) from the GEO dataset GSE45885." (PMID 36967804, 2023).
clear cell renal cell carcinoma (1 paper, 2025). "However, the clinical and biological significance of MKRN2 in clear cell renal cell carcinoma (ccRCC) has been minimally explored." (PMID 40959281, 2025).
Dysarthria (1 paper, 2020). Dysarthric speech is a general description referring to a neurological speech disorder characterized by poor articulation. "According to our results, lnc‐MKRN2‐42:1 expression levels were positively correlated with the severity of dyskinesia and dysarthria but were not correlated with other clinical symptoms, so only the correlation analysis for UPDRS III is presented here." (PMID 31814304, 2020).
fragile X syndrome (1 paper, 2023). A genetic syndrome caused by mutations in the FMR1 gene which is responsible for the expression of the fragile X mental retardation 1 protein. "In this way, we confirmed the interaction of FMR1, FXR1, and FXR2 of the Fragile X syndrome family as well as the E3 ubiquitin ligase MKRN2 with nsp3, both in context of single and nsp3/4 expression." (PMID 37905840, 2023).
gastric cancer (1 paper, 2022). A primary or metastatic malignant neoplasm involving the stomach. "In this study, using bioinformatics analysis and a series of experimental analyses, we found that an E3 ubiquitin-protein, MKRN2 was down-regulated in gastric cancer tissues." (PMID 35196650, 2022). "Overall, the present study suggests that MKRN2 may be a potential therapeutic target for gastric cancer." (PMID 35196650, 2022).
influenza (1 paper, 2024). An acute viral infection of the respiratory tract, occurring in isolated cases, in epidemics, or in pandemics; it is caused by serologically different strains of viruses (influenzaviruses) designated A, B, and C, has a 3-day incubation period, and usually lasts for 3 to 10 days. "With an obvious nuclear fraction of MKRN2 present in A549 cells, coupled with the significant accumulation of NP mRNA in the nuclei of MKRN2 depleted cells, we next analysed the effect of MKRN2 depletion on primary influenza mRNA transcripts." (PMID 38753876, 2024).
oligoasthenoteratozoospermia (1 paper, 2016). A form of male infertility that is characterized by a combination of low number or oligozoospermia, poor motility or asthenozoospermia, and abnormal shape or teratozoospermia of sperms. "MKRN2 protein levels were lower in human sperm samples from patients of oligoasthenoteratozoospermia (OAT) than in the normal samples." (PMID 28008940, 2016).
renal carcinoma (1 paper, 2025). A carcinoma arising from the epithelium of the renal parenchyma or the renal pelvis. "Nucleocytoplasmic separation assays revealed that MKRN2-OE occurred concurrently with β-catenin downregulation in both the cytoplasm and nuclei of renal cancer cell lines." (PMID 40959281, 2025). "Next, we found that in renal cancer cells, overexpression of MKRN2 led to elevated β-Catenin phosphorylation and reduced β-Catenin protein expression, resulting in the attenuation of Wnt pathway that is marked by the down-regulation of signature genes (c-Myc, Cyclin D, Axin2, Bcl-2, MMP2, and MMP9)." (PMID 40959281, 2025). "TUNEL fluorescence staining and flow cytometry suggested that MKRN2 overexpression (OE) increased apoptosis in renal cancer cells, while significantly suppressing proliferative capacity, cell invasion and migration, and wound-healing capacity in A498 and Caki-1 lines." (PMID 40959281, 2025). "Additionally, GSE40435 data indicated that MKRN2 was downregulated in renal cancer." (PMID 40959281, 2025). "MKRN2, ZNF598, UBE2D1, and TRIM25 were potential factors influencing renal cancer progression." (PMID 40959281, 2025).
renal cell carcinoma (1 paper, 2025). "According to BSP, the MKRN2 promoter region experienced significantly elevated methylation in five pairs of renal cell carcinoma tissues and adjacent tissues." (PMID 40959281, 2025).
tumor (5 papers, 2018 to 2025). "The β-catenin inhibitor ICG-001 did not affect MKRN2 protein expression, further validating the pivotal role of Wnt signaling in MKRN2-mediated apoptosis and tumor suppression." (PMID 40959281, 2025). "Specifically, MKRN2 functions as a tumor suppressor, by modulating the PPP2CA-β-Catenin axis to inactivate the Wnt pathway." (PMID 40959281, 2025). "In summary, MKRN2 suppresses ccRCC progression, primarily influencing tumor cell apoptosis via PPP2CA-mediated Wnt signaling." (PMID 40959281, 2025). "In a previous study, IGF2BP3 was reported to be regulated by the E3 ubiquitin ligase MKRN2, which is also a tumour suppressor." (PMID 37877353, 2023). "The results showed that tumor cell proliferation and colony formation were significantly inhibited in the MKRN2-overexpressed group in comparison with that in the control group." (PMID 35196650, 2022). "Clinical correlation analysis showed that the expression level of MKRN2 is related to the size and the degree differentiation of tumor." (PMID 35196650, 2022). "We then performed western blot analysis to detect MKRN2 protein levels in normal bronchial epithelial cells and commonly used NSCLC cell lines, finding that MKRN2 protein levels were lower in tumor cell lines than in normal bronchial epithelial cells." (PMID 30103781, 2018). "In tumor cells, MKRN2 promoter is marked by hypermethylation that lowers its gene transcription." (PMID 40959281, 2025). "In vivo experiments identified MKRN2 was a potential tumor inhibitor in ccRCC." (PMID 40959281, 2025). "MKRN2 silencing promotes tumor proliferation and migration by decreasing ubiquitination of IGF2BP3." (PMID 38565547, 2024). "Mounting evidence suggests that MKRN2 plays an important role in tumor growth and development." (PMID 35196650, 2022). "To determine whether an increase of MKRN2 expression suppresses the oncogenesis and growth of GC, we used nude mice bearing a subcutaneous xenograft tumor." (PMID 35196650, 2022). "However, downexpression of MKRN2 was found to be associated with low tumor differentiation and large tumor size, indicating that lack of MKRN2 promotes GC progression." (PMID 35196650, 2022). "As shown, MKRN2-OE markedly inhibited tumor burdens compared to the control vector group, while PPP2CA-OE reversed the growth inhibition upon MKRN2-OE." (PMID 40959281, 2025). "We found that MKRN2 inhibits the ERK signaling pathway, which plays a vital role in regulating tumor proliferation." (PMID 35196650, 2022). "Based on these findings, we propose that MKRN2 and PPP2CA have opposite regulatory effects on β-Catenin protein expression, leading to functional equilibration of the Wnt signaling that mediates ccRCC tumor progression." (PMID 40959281, 2025). "Furthermore, MKRN2 mRNA and protein expression in the four ccRCC cell lines and samples was significantly downregulated from levels in human normal kidney epithelial cells (HEK293) and paired adjacent non-tumor tissues." (PMID 40959281, 2025). "Furthermore, we found that MKRN2 inhibited cell migration and invasion in NSCLC cells by regulating the expression of RhoA/ROCK1 and MMP9, thereby influencing the malignant behavior of tumor cells." (PMID 30103781, 2018).
cancer (3 papers, 2018 to 2023). A tumor composed of atypical neoplastic, often pleomorphic cells that invade other tissues. "Among the 82 paired samples, the expression level of MKRN2 in 28 cancer tissues was only half that in the adjacent cancer tissues." (PMID 35196650, 2022). "We then evaluated how MKRN2 interacts with PI3Kp85α to activate the Akt-signaling pathway to promote cancer-cell migration and invasion." (PMID 30103781, 2018). "In summary, our findings indicated that MKRN2 played a critical role in regulating the progression of NSCLC through inhibition of cancer-cell metastatic potential." (PMID 30103781, 2018). "MKRN2 may function as a cancer–testis antigen, with dual roles in tumorigenesis and spermiogenesis that need to be further investigated." (PMID 36967804, 2023). "Moreover, we examined MKRN2 expression in NSCLC tissues and cell lines by immunohistochemistry and western blot and altered MKRN2 expression in these cells to evaluate changes in cancer-related phenotypes in order to determine its role in NSCLC." (PMID 30103781, 2018). "Therefore, in contrast to previous studies, our findings suggested that MKRN2 might participate in different biological mechanisms in cancer cells." (PMID 30103781, 2018). "Our results indicated that MKRN2 played a critical role in NSCLC by inhibiting cancer-cell metastatic potential through the PI3K/Akt-signaling pathway, suggesting MKRN2 as a candidate prognostic biomarker and possible therapeutic target in NSCLC." (PMID 30103781, 2018). "Co-IP and western blot analyses showed that MKRN2 could mediate the ubiquitination of PKM2, which promotes cancer proliferation." (PMID 35196650, 2022).
infection (1 paper, 2024). The state of being infected such as from the introduction of a foreign agent such as serum, vaccine, antigenic substance or organism. "After validation of the MKRN2 siRNA pool by Western blotting, we performed multicycle infections of A549 MKRN2 depleted cells with A/WSN/33, the 2009 pandemic H1N1 A/California/7/2009 virus and an H3N2 A/Norway/466/2014 strain." (PMID 38753876, 2024). "While, in single round infections similar to that of Cal09, mRNA levels were also significantly lower when MKRN2 was depleted." (PMID 38753876, 2024). "We first visualised the subcellular distribution of MKRN2 over the course of a A/WSN/33 infection in our A549-MKRN2 overexpression cells." (PMID 38753876, 2024). "Alongside the relocalisation of MKRN2 during infection this prompted us to investigate if MKRN2 aids IAV mRNA export, which would in turn prevent their degradation mediated by nuclear retention." (PMID 38753876, 2024). "As we observed this inhibitory phenotype early in infection, we wanted to better understand the role MKRN2 may play at this stage of the IAV replication cycle." (PMID 38753876, 2024). "This suggests a role of MKRN2 in regulating viral mRNA early in infection." (PMID 38753876, 2024). "Therefore, we sought to determine the localisation of IAV mRNAs during infection of MKRN2 depleted cells." (PMID 38753876, 2024).
MKRN2 also shares sentences with these, for which no sentence is quoted: autism (1 paper); central precocious puberty (1); colorectal cancer (1); colorectal tumors (1); COVID-19 (1); Dyskinesia (1); male fertility (1); metabolic disorders (1); neurodevelopmental disorder (1); neurological disorders (1); osteoarthritis (1); papillary thyroid cancer (1); Parkinson disease (1); schizophrenia (1); systemic lupus erythematosus (1); teratozoospermia (1); virus infection (1).